SRSF5 (serine and arginine rich splicing factor 5)
Description:
Plays a role in constitutive splicing and can modulate the selection of alternative splice sites.
Synonyms: HRS; SFRS5; SRP40
Tractability: PROTAC: ubiquitination databases record sites on it; its protein half-life has been measured.
Gene: Protein-coding gene on chromosome 14 (69,726,893 to 69,773,904, forward strand). Ensembl gene ENSG00000100650.
Subcellular location: Nucleus
Subcellular location (Human Protein Atlas): Nucleoplasm; Cytosol; Nucleoli
Pathways (Reactome):
Metabolism of RNA: Processing of Capped Intron-Containing Pre-mRNA; Transport of Mature mRNA derived from an Intron-Containing Transcript; mRNA 3'-end processing; mRNA Polyadenylation; mRNA Splicing - Major Pathway
Disease: Dengue Virus-Host Interactions
Gene Ontology:
Molecular function: protein binding; RNA binding; nucleic acid binding; protein kinase B binding; RS domain binding
Biological process: mRNA processing; mRNA splice site recognition; regulation of alternative mRNA splicing, via spliceosome; cellular response to insulin stimulus; liver development; liver regeneration; positive regulation of RNA splicing; response to insulin; RNA splicing, via transesterification reactions
Cellular component: nucleoplasm; nuclear speck; nucleus
Genetic constraint (gnomAD): Loss-of-function variants: 5 observed, 33.39 expected, observed/expected ratio (o/e) 0.15, 90% interval 0.077 to 0.31. The synonymous counts are far from expectation, so gnomAD's model fits this gene poorly and the ratio says little. Missense variants: 223 observed, 370.48 expected, observed/expected ratio (o/e) 0.6, 90% interval 0.54 to 0.67. Synonymous variants: 164 observed, 125.36 expected, observed/expected ratio (o/e) 1.31, 90% interval 1.15 to 1.49.
Homologues: Orthologues: chimpanzee SRSF5 (100% identical), macaque SRSF5 (100% identical), dog SRSF5 (99% identical), rabbit SRSF5 (99% identical), guinea pig SRSF5 (98% identical), mouse Srsf5 (98% identical), pig SRSF5 (98% identical), rat Srsf5 (98% identical), tropical clawed frog srsf5 (91% identical), zebrafish srsf5b (74% identical). Paralogues in human: SRSF4 (61% identical), SRSF6 (61% identical), SRSF1 (38% identical), SRSF7 (29% identical), SRSF9 (29% identical), SRSF3 (24% identical), RSRC2 (22% identical), RSRP1 (19% identical).
Diseases named in the same sentence as SRSF5 in open-access papers:
SRSF5 is named in the same sentence as 33 diseases in open-access papers, as found by Europe PMC text mining. Sharing a sentence is not in itself a finding about the gene and the disease. The quoted sentences say what the papers report.
lung carcinoma (7 papers, 2010 to 2025). "Among the SR proteins family, abnormal expression of SRSF5 has been reported in breast, renal, and lung cancers, and it was involved in AS events in prostate and lung cancers." (PMID 39915450, 2025). "SRSF5 has been shown to modulate apoptosis in lung cancer by controlling the alternative splicing of CCAR1." (PMID 37190199, 2023). "To this end, we examined SRSF5 expression levels in 60 pairs of human lung cancer samples and their matched normal lung epithelial tissues by immunohistochemical (IHC) analysis." (PMID 29942010, 2018). "SRSF5 regulates tumorigenesis of lung cancer cells through AS of CCAR1 pre-mRNA, and aberrant alternative splicing is a major contributor to cancer development." (PMID 29942010, 2018). "Upregulation of SRSF5 (2-fold) occurred in 22 of 60 (36.67%) clinical lung cancer samples compared with the paired normal tissues (red columns)." (PMID 29942010, 2018). "Together, these results indicate that SRSF5 is involved in human lung cancer development, probably through regulating alterative splicing of CCAR1 pre-mRNA." (PMID 29942010, 2018). "We also found that abnormal hyperacetylation of SRSF5 promotes the development of human lung cancer." (PMID 29942010, 2018). "The staining of total SRSF5 and acetylated SRSF5 increased, while the Smurf1 expression level decreased moderately, in lung cancer samples compared with their adjacent tissues and accumulation of positive signals in nucleus were observed." (PMID 29942010, 2018). "We here propose SRSF5 as a potent oncogenic factor, at least in the context of lung cancer development." (PMID 29942010, 2018). "Third, SRSF5 acetylation as well as total protein levels were upregulated in human lung cancers and correlated with cancer progression." (PMID 29942010, 2018). "The increased acetylation of SRSF5 in human lung cancers is conducive to stabilization of SRSF5 and activation of AS of CCAR1, which further promotes the tumor growth." (PMID 29942010, 2018). "Depletion of SRSF5 in A549 and H358 lung cancer cells dramatically suppressed cell proliferation and tumor growth." (PMID 29942010, 2018). "To provide more evidence that the modification of SRSF5 mediates the metabolic stress response of lung cancer cells, we established three A549 stable lines that knocked down endogenous SRSF5 and then further introduced SRSF5 WT or the K125R, K125Q mutants." (PMID 29942010, 2018). "Importantly, SRSF5 is hyperacetylated and upregulated in human lung cancers, which correlates with increased CCAR1S expression and tumor progression." (PMID 29942010, 2018). "We next asked whether expression of SRSF5 as well as acetylated SRSF5 is abnormally altered in clinical lung cancers." (PMID 29942010, 2018). "Overexpression of SRSF5 and SRSF7 in lung cancer and colorectal cancer tissues, and knockdown of SRSF7 induced apoptosis in colorectal and lung cancer cells." (PMID 39286028, 2024). "Our current findings suggest that SRSF5 promotes tumor growth largely dependent on the splicing of CCAR1, at least in lung cancer cells." (PMID 29942010, 2018). "Fourth, SRSF5 expression was positively correlated with more oncogenic CCAR1S and less pro-apoptotic CCAR1L, both in cancerous cell lines and in human lung cancer tissues." (PMID 29942010, 2018).
breast carcinoma (5 papers, 2012 to 2023). "Previously SRSF5 expression has been shown to be increased in breast cancer, where it was associated with changes in alternative splicing of CD44 as well as lymph node metastasis." (PMID 23284704, 2012). "Conversely, ER +ve breast cancer patients with high SRSF5 expression had a reduced risk ratio." (PMID 37190199, 2023). "Modulating the activity of SRSF5 in ER +ve breast cancer will be a potential approach to combating TAM resistance." (PMID 37190199, 2023). "Our findings thus also indicate that SRSF5 expression can modulate the TAM response in ER +ve breast cancer." (PMID 37190199, 2023). "Immunohistochemistry was employed to determine SRSF5 and BQ expression in 137 breast cancer samples." (PMID 37190199, 2023). "The expression of SRSF5 is low in TAM-resistant breast cancer cells." (PMID 37190199, 2023). "Despite the clear involvement of SRSF5 in MCF-7 and MDA-MB-231 breast cancer cells, this SR protein did not appear to be involved in the alternative splicing of Mcl-1 in JAR cells." (PMID 23284704, 2012).
glioma (3 papers, 2021 to 2023). A benign or malignant brain and spinal cord tumor that arises from glial cells (astrocytes, oligodendrocytes, ependymal cells). "To determine the effect of SRSF5 overexpression (OE), we transfected the patient-derived glioma cell line U87 with plasmids expressing SRSF5 or empty-vector controls (“Materials and methods” section)." (PMID 33499924, 2021). "Additionally, we used TCGA to identify co-interaction networks involving SRSF5 and GTEx and TCGA to evaluate the expression of these factors in NBT and glioma tissues, with the five molecules showing the highest expression selected for qRT-PCR verification." (PMID 36064747, 2022).
oral squamous cell carcinoma (3 papers, 2021 to 2025). "SRSF5 and SRSF3 were reported to be overexpressed in oral squamous cell carcinoma (OSCC), and necessary for OSCC cell proliferation, cell cycle progression, and in vivo tumor formation." (PMID 40938473, 2025).
pancreatic cancer (3 papers, 2021 to 2023). "Thus, our results suggest that CLK1-mediated phosphorylation of SRSF5 on Ser250 is a potential mechanism underlying the pro-oncogenic functions of CLK1 in pancreatic cancer." (PMID 33849617, 2021). "Previous studies have found that SRSF5 can regulate the m6A methylation of pancreatic cancer, thus promoting its growth and metastasis." (PMID 34733794, 2021). "The results showed that when CLK1 was at a high expression level, pancreatic cancer patients with high expression levels of SRSF5 have a poorer prognosis than those with low SRSF5 expression levels." (PMID 33849617, 2021). "In addition, inhibited exon skipping of METTL14 and enhanced exon skipping of Cyclin L2 caused by CLK1’s enhancing SRSF5 SRSF5250-Ser phosphorylation enhanced the N6-methyladenosine modification level and cancer aggressiveness in pancreatic cancer." (PMID 36977668, 2023). "However, the functions of SRSF5 in pancreatic cancer have not been intensively elucidated." (PMID 33849617, 2021).
prostate carcinoma (3 papers, 2020 to 2022). A carcinoma that arises from epithelial cells of the prostate gland. "In prostate cancer cells, it was demonstrated that the expression and phosphorylation levels of SRSFs proteins (particularly on SRSF5) are significantly increased in hypoxia." (PMID 35883682, 2022). "On the other hand, SRSF5 is indicated to be involved in pre-mRNA splicing of Kruppel-like factor 6 (KLF6) in prostate cancer." (PMID 32106418, 2020). "In addition to SRSF1, the roles of SRSF5 in breast and prostate cancers have been reported." (PMID 32106418, 2020).
lymph node metastasis (2 papers, 2012 to 2017). "SRSF5 expression is increased, associated with lymph node metastasis, and involved in the production of the anti-apoptotic form of Mcl-1 in breast cancers." (PMID 28536481, 2017).
non-small cell lung carcinoma (2 papers, 2020 to 2024). A group of at least three distinct histological types of lung cancer, including non-small cell squamous cell carcinoma, adenocarcinoma, and large cell carcinoma. "In addition, a preliminary study showed that SRSF5 knockdown inhibited glycolysis and cell proliferation by decreasing PKM2 expression in non-small cell lung cancer cells, although the detailed mechanism was unclear." (PMID 38263157, 2024).
germ cell tumor (1 paper, 2017). A benign or malignant, gonadal or extragonadal neoplasm that originates from germ cells. "Immunohistochemical studies demonstrated that SRSF5 was constitutively expressed in male germ cells and the level was decreased in human testicular germ cell tumors." (PMID 28536481, 2017). "In testicular germ cell tumors, expression of SRSF5 protein was higher in non-seminomas than pure seminomas and the seminoma components of mixed germ cell tumors (P < 0.0001), although the levels were lower than that of normal germ cells." (PMID 28536481, 2017).
head and neck squamous cell carcinoma (1 paper, 2025). A squamous cell carcinoma that arises from any of the following anatomic sites: lip and oral cavity, nasal cavity, paranasal sinuses, pharynx, larynx, and salivary glands. "Despite the lack of information on the regulatory mechanisms of VEGF-Axxxa and VEGF-Axxxb, overexpression of splicing regulatory factors (SRSF1, SRSF5, SRSF5, and SRPK1) has been associated with the upregulation of VEGF-Axxxa isoforms in head and neck squamous cell carcinomas patients." (PMID 40282556, 2025).
hepatocellular carcinoma (1 paper, 2021). A malignant tumor that arises from hepatocytes. "Three splicing factors, CELF2, ESRP2 (epithelial splicing regulatory protein 2), and SRSF5 (serine- and arginine-rich splicing factor 5), which are substantially downregulated in hepatocellular carcinoma samples, were found to be responsible for splicing dysregulation in hepatocellular carcinoma." (PMID 34681716, 2021).
Hypothermia (1 paper, 2017). Reduced body temperature due to failed thermoregulation. "Hypothermia also induced SRSF5 protein in mouse embryonic fibroblasts derived from wild-type and CIRP-knockout (KO) mice, NIH/3T3 cells, human HEK293 cells and NC65 cells." (PMID 28536481, 2017).
influenza (1 paper, 2022). An acute viral infection of the respiratory tract, occurring in isolated cases, in epidemics, or in pandemics; it is caused by serologically different strains of viruses (influenzaviruses) designated A, B, and C, has a 3-day incubation period, and usually lasts for 3 to 10 days. "Further studies are needed to evaluate the contribution of viral polymerase to SRSF5‐mediated splicing of viral genes in different influenza subtypes." (PMID 36257906, 2022). "In summary, we highlighted the functional importance of SRSF5 in promoting IAV replication through the up‐regulation of M2 derived from alternative splicing of M mRNA, and provided strong preclinical evidence for repositioning anidulafungin as an anti‐influenza drug that targets SRSF5." (PMID 36257906, 2022).
metastatic cancer (1 paper, 2021). A carcinoma which has spread from the original site of growth to another anatomic site. "Kim and colleagues identified the related SRSF5 as a novel detection marker for pleural metastatic cancer cells." (PMID 33905374, 2021).
osteosarcoma (1 paper, 2024). A usually aggressive malignant bone-forming mesenchymal neoplasm, predominantly affecting adolescents and young adults. "We identified 6 splicing factor genes associated with the prognosis of osteosarcoma patients, namely SRSF1, SRSF4, SRSF5, SRSF7, SRSF8, and SRSF10." (PMID 39286028, 2024).
small cell lung carcinoma (1 paper, 2018). Small cell lung cancer (SCLC) is a highly aggressive malignant neoplasm, accounting for 10-15% of lung cancer cases, characterized byrapid growth, and early metastasis. "SRSF5–7 are upregulated in small cell lung cancer (SCLC), and SRSF5 has diagnostic potential in SCLC and extrapulmonary pleural metastatic cancer." (PMID 29789787, 2018).
tuberculosis (1 paper, 2022). A chronic, recurrent infection caused by the bacterium Mycobacterium tuberculosis. "Furthermore, we validated the accuracy of some differentially expressed genes in an independent cohort using quantitative PCR, and obtained three novel genes (RBM3, CSRNP1, SRSF5) with the ability to discriminate active tuberculosis from LTBI and HC." (PMID 36059536, 2022).
cancer (18 papers, 2012 to 2025). A tumor composed of atypical neoplastic, often pleomorphic cells that invade other tissues. "SRSF5 is reported to promote cancer development and progression by regulating the splicing of multiple genes, including ETS1, METTL14, Mcl-1, Cyclin L2, and CCAR1." (PMID 38263157, 2024). "As expected, in ER +ve cases, the low expression of SRSF5 was significantly associated with TAM resistance (p = 0.015) and local cancer recurrence (p = 0.024) and metastasis (p = 0.002) as indicated by a chi-square test." (PMID 37190199, 2023). "SRSF5 was reported to promote cell growth, especially in cancer cells, and is, therefore, also considered an oncogene." (PMID 37894498, 2023). "Univariate analysis showed that protein levels of SRSF5 were significantly different between paired normal and cancer samples (P < 0.001)." (PMID 29942010, 2018). "This study demonstrated that LINC01852 acts as a molecular scaffold to facilitate the interaction between SRSF5 and TRIM72, promoting TRIM72-mediated degradation of SRSF5, and these findings reveal a novel lncRNA-based mechanism that regulates SRSF5 expression and function in cancer cells." (PMID 38263157, 2024). "As expected, a low expression of SRSF5 was associated with TAM resistance, local cancer recurrence and metastasis since ineffective TAM treatment can result in cancer recurrence and metastasis." (PMID 37190199, 2023). "A recent study revealed that SRSF5 can increase the protein expression of PKM2, a key factor regulating the “Warburg effect” in cancer cells." (PMID 38263157, 2024). "Of the many downregulated spliceosome complex proteins in cancer, we captured the interactions between SNRNP70, SRSF5, DDX17 and LUC7L3 in the largest component of the projected downregulated network." (PMID 34728699, 2021). "Previous studies have demonstrated that most SRSFs were extensively dysregulated with oncogenic roles through regulating the AS of various cancer-related genes in many cancers such as lung (SRSF1, SRSF5), breast (SRSF3), colon (SRSF1, SRSF10), liver cancers (SRSF2), and glioma (SRSF1, SRSF3)." (PMID 37558679, 2023). "The negative correlation of SRSF5 expression with BQ overexpression was further examined using the primary cancer samples in the tissue microarray (TMA) to validate this notion." (PMID 37190199, 2023). "SRSF5 and SRSF6 play important roles in the development and progression of cancers." (PMID 36289466, 2022). "However, when specific to certain cancer types or genes, this negative correlation did not hold, such as SRSF1 in LUSC and KICH; SRSF4 in TGCT, and SRSF5 in LAML and MESO (p < 0.05)." (PMID 38015716, 2023).